TLR7 (toll like receptor 7)
Diseases named in the same sentence as TLR7 in open-access papers (continued):
Sharing a sentence is not in itself a finding about the gene and the disease.
tumor (continued). "Here we report the development of an X-ray-activated nanomotor, GM-R848, comprising an iron carbonyl (FeCO) prodrug framework encapsulating the TLR7 agonist resiquimod (R848), designed for efficient tumor cell elimination and immune activation." (PMID 41142429, 2025). "In the B16-OVA melanoma model, local administration of TLR7/8 agonists polarizes Th1 responses, affecting anti-tumor immunity, and activates NK cells and CD8+ T cells." (PMID 41488647, 2025). "Their findings revealed significantly higher accumulation of the TLR7 agonist at the tumor site compared to free drug administration." (PMID 41228373, 2025). "Ligation of TLR7 in the K-ras mouse model vigorously accelerated tumor progression, interfaced with canonical NF-κB/MAPK cascades, induced STAT3 activation and caused loss of p16 and PTEN." (PMID 41465346, 2025). "Strikingly, they found that the combination of systemic IFNα and local IMQ administration markedly upregulated TLR7 expression on cDCs (cDC1 and cDC2) within the tumor microenvironment (TME)." (PMID 40547481, 2025). "Imiquimod activates the toll-like receptor 7 (TLR7), triggering a local immune response and tumor regression." (PMID 41228308, 2025). "Immune modulation: Tumour-derived EVs containing miR-21 and miR-29a bind Toll-like receptors (TLR7/8) on immune cells, triggering an NF-κB–mediated inflammatory cascade (↑TNFα, IL-6) that promotes tumour growth and metastasis." (PMID 41311647, 2025). "TLR7 plays a pivotal role in regulating immune cell ratios within the tumor microenvironment to exert antitumor functions." (PMID 39857735, 2025). "Our combined treatment exploits the immunostimulatory properties of both IFNα and TLR7/8 signaling and is effective in the treatment of primary tumors, while protecting form metastasis and tumor relapse by inducing immunological memory." (PMID 39849091, 2025). "The ability to integrate personalized neoantigen recognition with TLR7‐driven innate immune activation positions this approach as a promising strategy to overcome the immunosuppressive tumor microenvironment in PDAC." (PMID 40498983, 2025). "These primed DCs produce IL-12 in response to topical IMQ treatment through TLR7–c-Jun signaling, which then blocks angiogenesis and induces tumor necrosis at the local sites." (PMID 39849091, 2025). "Imiquimod, a TLR7/8 agonist, stimulates natural killer cells to eliminate tumor cells, which release tumor antigens and stimulate CD4+ T cells specific to the tumor." (PMID 40727443, 2025). "The synergistic effects of tumor antigen release and TLR7/8 pathway activation promote systemic anti-tumor immunity by enhancing DCs maturation, M1 macrophage polarization, and cytotoxic T lymphocyte infiltration." (PMID 41142429, 2025). "Nevertheless, TLR7/8 activation by R848 alone was sufficient to reject the smaller developed tumor in CNS-1." (PMID 40727443, 2025). "TLR7 is similarly affected, which is responsible for promoting tumor progression, resistance to chemotherapy, and, as the study indicates, poor clinical results." (PMID 38792335, 2024). "Not only was reduction in tumor growth abrogated in TLR7-/- mice after FluVx treatment, but the prolonged survival was also diminished." (PMID 38476365, 2024). "A recent study has shown that tumor-derived pDCs were significantly dampened in IFN-α production upon TLR7/9 activation in HPV-negative HNSCC, but were functionally uncompromised in HPV-positive HNSCC." (PMID 39020402, 2024). "A novel injectable TLR7/8 dual agonist, 3 M-052, triggered innate immunity and activated systemic tumor-specific CD8+ T cell immunity, leading to the rejection of distant uninjected tumors without systemic cytokine release and toxicity." (PMID 39020402, 2024). "Lastly, we observed that sustained local stimulation of TLR7/8 at the time of tumor resection augments resection-mediated disruption to the immunosuppressive TME and induces systemic T cell trafficking." (PMID 39399681, 2024).
tumor (continued). "CT had the ability to promote anticancer M1 polarization via the TLR7/MyD88/NF-κB axis as well as induce an anti-tumour CD8+ response (Ref." (PMID 39320855, 2024). "TLR3 and TLR7 identification of viral-based PAMPs inside the tumor microenvironment is thought to initiate antitumor immunity following intratumoral FluVx therapy." (PMID 38476365, 2024). "Since monocytes are known to express the DSP-0509 target molecule TLR7, it is reasonable to attribute the strength of the anti-tumor activity of the combination with RT to strong DSP-0509-induced activation of monocytes via TLR7 signal upregulation." (PMID 39054418, 2024). "Recent research has indicated that vaccines containing tumor antigen peptides and a TLR7/8 agonist exhibit superior anti-tumor effects when administered intravenously compared to subcutaneous injection." (PMID 38523155, 2024). "The dual role of TLR9 and TLR7 in cancer is complex and their effects can be context-dependent, depending on various factors, including the specific type of cancer and tumor stage." (PMID 38850110, 2024). "Imiquimod, a synthetic TLR7 agonist approved for basal cell carcinoma, remains a successful illustration of in situ activation of TA-pDCs translating into tumor regression." (PMID 39575246, 2024). "This innovative approach, through the co-delivery of the PS Ce6 and cholesterol-bound R848 (Chol-R848) to tumor sites, not only triggers ICD via Ce6-mediated PDT but also specifically targets TLR7/8 within the tumor." (PMID 38607182, 2024). "Human pDC cell line GEN2.2, stimulated with TLR7/9 agonists, is able to lyse tumor cells in a TRAIL-dependent manner." (PMID 39020402, 2024). "TLR-7 agonists have demonstrated significant immunostimulatory and anti-tumor efficacy in various cancer models." (PMID 39318624, 2024). "To further examine the role of TLR7 in tumor outcomes from FluVx treatment, we observed survival of FluVx-treated WT and TLR7-/- mice." (PMID 38476365, 2024). "The fact that targeting of TLR7 agonists to FRβ+ TAMs/MDSCs leads to a significant reduction in tumor growth suggests that FRβ+ TAMs/MDSCs are naturally immunosuppressive." (PMID 38384467, 2024). "We showed that anti-tumor activity is enhanced by combining RT with the TLR7 agonist DSP-0509 in the CT26, LM8, and 4T1 inoculated mice models." (PMID 39054418, 2024). "Additional ongoing studies include the examination of cholesterolized liposome formulations of TLR7 agonists, which have shown potential in reducing tumor growth through effective delivery and activation of immune responses within the lymph nodes." (PMID 38732254, 2024). "Exosomes produced by tumor cells in chronic lymphocytic leukemia activate TLR7 to mediate PD-L1 production in monocytes and release cytokines that stimulate tumor growth." (PMID 38195554, 2024). "TLR-7 is responsible for promoting tumor progression and chemotherapy resistance, as well as, according to the study, poor clinical outcomes." (PMID 39124797, 2024). "The M3-day 1687 time point (tumor locally treated with TLR7 agonist) showed convolution of T cell repertoires with a greater TCR network connectivity than the previous time points, based on metrics such as density, average clustering coefficient and S-metric." (PMID 38383522, 2024). "Intratumoral FluVx therapy reveals the anticancer potential of TLR signaling, with TLR7 identified as a factor to tumor progression reduction." (PMID 38476365, 2024). "In NSCLC, TLR7 signaling contributes to immune evasion by suppressing the activity of CTLs by recruiting immunosuppressive MDSCs to the tumor microenvironment, facilitating tumor progression and metastasis." (PMID 38850110, 2024). "For example, clinical trials combining TLR3 and TLR7/8 agonists with cancer vaccines have led to disease stabilization and tumor regression in some patients." (PMID 39451226, 2024). "Recent studies revealed variable data regarding TLR7 tumor suppressing role in various cancer types, including OSCC." (PMID 38850110, 2024).
tumor (continued). "In a mouse model of GC, vaccination with a TLR7 agonist conjugated with a GC tumor antigen resulted in a reduction in tumor size by inducing a cytotoxic T cell response." (PMID 38927922, 2024). "In an approach leveraging both conjugation and self‐assembly, peptides conjugated to TLR7/8 agonists and self‐assembled into 20 nm particles were shown to boost T cell immunity and tumor eradication." (PMID 38193112, 2024). "TLR7 agonists demonstrate potent immunostimulatory activity to fight against many types of tumors through the induction of tumor-specific immune responses." (PMID 38203835, 2024). "Imiquimod is an imidazoquinoline amine that shows immune modulating and anti-tumor effects by binding to TLR7, mainly expressed by plasmacytoid DCs, macrophages, mast cells, and monocytes." (PMID 38675755, 2024). "Here, we explore the effect of local and controlled release of TLR7/8 agonist from a polymer scaffold implanted at the time of tumor resection." (PMID 39399681, 2024). "It has been suggested that TLR7/8 activation promotes tumors by inducing robust pro-inflammatory cytokine secretion and activating NK at the tumor site." (PMID 39000607, 2024). "In such cases, TLR inhibitors such as OPN-301 (anti-TLR2) and other TLR7/9 inhibitors have shown the potential to inhibit tumor growth in preclinical models." (PMID 39451226, 2024). "TLR7-treated CB-pDCs in co-cultures with CRC tumor digest induced a broad spectrum of cytokines and chemokines associated with T and NK cell trafficking and potential cytolytic function alongside macrophage and cDC recruitment." (PMID 39575246, 2024). "In this manner, these TLR7-mediated pro-inflammatory effects would synergize with the anti-CD200R agonist to facilitate anti-tumor responses." (PMID 38137547, 2023). "An anti-PD-L1 conjugated to the TLR7/8 agonist D18 has very recently been disclosed with promising preliminary results, including a potent anti-tumor activity in the B16 melanoma model which is a PD1-resistant model." (PMID 36650546, 2023). "As a result, the Smac-TLR7/8 hydrogel improved the anti-tumor activities of the macrophages, directed the phagocytosis of tumor cells, and increased the secretion of TNF." (PMID 36721212, 2023). "Many imidazoquinolines are synthetic TLR activators, including resiquimod (R848), a potent dual TLR7/8 agonist that has recently gained attention as a cancer immunotherapy agent due to its ability to reprogram TAMs in subcutaneous tumor models." (PMID 36774352, 2023). "Imiquimod, a TLR7 agonist, activates immune responses and enhances anti-tumor activity by triggering TLR7." (PMID 37049910, 2023). "Intratumoral administration of SZU101(another TLR7 agonist) triggers a systemic anti-tumor response and alters the TME by increasing CD4+ and CD8+ cells while reducing Treg cells in a murine breast tumor model." (PMID 37936697, 2023). "Another work in the B16.F10 model also demonstrated that TLR7/9 stimulation with imiquimod can trigger CCL2 release by MCs to efficiently recruit plasmacytoid DCs at the tumor site, which, in turn, can directly kill tumor cells via TRAIL and granzyme B." (PMID 37376140, 2023). "The scoring signature is constructed by three genes (IL1A, NT5E, and TLR7), whose expression in the tumor is significantly higher than normal both in the TCGA cohort and our PKUCH cohort." (PMID 36979463, 2023). "In chronic lymphocytic leukaemia, the non-coding Y RNA hY4 enriched in tumour exosomes induces the expression of PD-L1 on monocytes via stimulation of endosomal TLR7 signalling, thus promoting tumour escape." (PMID 39698297, 2023). "In this study, we clarified that DSP-0509 activated the innate immune system via TLR7, which in turn resulted in activation of the adaptive immune system, and that it showed anti-tumor activity." (PMID 36793737, 2023). "The TCGA database was then used to examine differences in TLR7 expression levels between tumor and normal tissues, revealing the specificity of TLR7 expression." (PMID 37362864, 2023).
tumor (continued). "These two studies showed that TLR7/8 agonists activated tumor-intrinsic mechanisms related to survival and treatment resistance." (PMID 37112730, 2023). "In conclusion, we expect that DSP-0509, a new TLR7 agonist that synergistically induces anti-tumor effector memory T cells with immune checkpoint blockers (ICBs) and can be administered systemically, will be used in the treatment of multiple cancers." (PMID 36793737, 2023). "Recent approach in TLR7 agonist drug discovery is focusing on tumor targeting modality including ADC and nanoparticle and so on." (PMID 36793737, 2023). "As well as being candidate vaccine adjuvants, synthetic TLR7/8 agonists have potent anti-tumor activity when used alone or in combination with immunotherapies." (PMID 36319717, 2023). "Further work is required to more precisely dissect the roles of TLR7 and its ligands in different populations of epithelial and stromal cells and to understand their relative contributions to tumor progression." (PMID 36602302, 2023). "Immune-stimulating antibody conjugates (ISACs) are based on tumor-targeting monoclonal antibodies (mAbs) functionalized with small molecule agonists of Toll-Like Receptors 7 and 8 (TLR7/8) such as imidazoquinoline derivatives (IMDs)." (PMID 38125888, 2023). "Leveraging these unique attributes of ProLNG-001 fosters tumor regression by stimulating Th1-polarized cytotoxic T cells and tumor-infiltrated NK cells through the immune response mediated by TLR7/8 receptors." (PMID 37766179, 2023). "Preclinical data suggest that the activation of TA-pDCs by TLR-7/9 agonists administration amplifies the local and systemic anti-tumor immune response and promotes tumor cells killing." (PMID 38239354, 2023). "As a next step, we evaluated the anti-tumor effects of DSP-0509 in syngeneic tumor-bearing mouse models as DSP-0509 was shown to have TLR7 agonistic activity and to activate the immune system in vivo." (PMID 36793737, 2023). "TLRs like TLR7, 8, and 9 can sense foreign nucleic acids, and their subsequent activation on NK cells empowers anti-tumor immune responses." (PMID 37936697, 2023). "We were particularly interested in the monocytes’ response to the TLR7/8 agonist since TLR7/8 has been shown to increase tumor cell proliferation in human PDAC and a TLR7/8 agonist has been shown to prolong survival in a PDAC mouse model." (PMID 37575220, 2023). "In preclinical models, an anti-HER2 ISAC with TLR7/8 antagonist effectively resulted in tumor elimination in mouse models." (PMID 37569276, 2023). "Here, the authors generate a nanoparticle encapsulating the TLR7/8 agonist, R848, which induces tumour regression in mice by reprogramming myeloid cells independently of T and NK cells." (PMID 36774352, 2023). "This study discovered a strong positive correlation between TLR7 expression and nearly every tumor ESTIMATE score." (PMID 37362864, 2023). "TLR7 expression, survival prognosis, gene mutation, MMR, MSI, TMB, tumor immune microenvironment, functional pathways, and drug sensitivity were all demonstrated in a pan-cancer analysis." (PMID 37362864, 2023). "One significant study involves the utilization of a self-assembled nano-vaccine platform that combines a conjugate of Toll-like receptor 7/8 agonist and tumor epitope (TLR7/8a-epitope)." (PMID 37504412, 2023). "Several TLR7 functions were involved in regulating the tumor immunology of specific tumors, as investigated in the present study." (PMID 37362864, 2023). "Another TLR7/8 dual agonist ISACs conjugated to tumor-targeting antibodies induced a robust localized activation of macrophages and DCs leading to tumor clearance and immunological memory." (PMID 37925462, 2023). "Tumor cells can induce TLR-mediated NF-κB activation and protumoral inflammatory process by secreting a large number of EXOs containing miRNA-21 and miRNA-29a and binding to TLR8 and TLR7 in immune cells, leading to tumor growth and metastasis." (PMID 37680720, 2023).
tumor (continued). "On the same principle, tumor cell membranes were encapsulated with nanoparticles coloaded with PDT, TLR7 agonists, and tumor antigens (CCMV/LTNPs)." (PMID 38140108, 2023). "TLR stimulation, particularly TLR7/8/9 stimulation, is shown to overcome suppression of T cell proliferation by tumor-infiltrating neutrophils." (PMID 37317970, 2023). "In a preclinical mouse model, BDC-1001 an ISAC comprising a dual TLR7/8 agonist conjugated to HER2-targeted antibodies elicited a localized immune response resulting in tumor reduction of myeloid and T cells and immunological memory." (PMID 36966267, 2023). "Instead, results were obtained by different combinations of a tumor cell or bone marrow cell grafting and treatment with TLR7 agonists or inhibitors." (PMID 36602302, 2023). "With a TLR7 agonist, it is possible to enhance the efficacy of chemotherapy or facilitate the killing of cytotoxic T cells through increased tumor immunogenicity." (PMID 36851155, 2023). "TLR7 is an innate immune receptor that recognizes single-stranded RNAs, and its activation leads to anti-tumor immune effects." (PMID 36793737, 2023). "Similar data showing that the combination of TLR7/8 ligands with RT improves local and distant tumor control has been reported in murine tumor models of GI cancer, lymphoma, fibrosarcoma, lung and pancreatic cancer." (PMID 37112730, 2023). "As TLR7 was a differential expression in tumor and normal tissue, we further investigated TLR7 expression analysis in a single cell." (PMID 37362864, 2023). "This platform was composed of a photosensitizer chlorin e6 (Ce6), and a toll-like receptor-7 (TLR-7) agonist (imiquimod (R837)) as the immune adjuvant, together with aCTLA-4 was able to target tumor growth effectively." (PMID 37735656, 2023). "TransCon TLR7/8 Agonist was characterized for resiquimod release in vitro and in vivo, in mice and rats, and was assessed for anti-tumor efficacy and pharmacodynamic activity in mice." (PMID 36123697, 2022). "In this study, with the help of the TLR7/8 agonist-conjugated radiosensitive peptide hydrogel, tumor-promoting and radio-resistant M2 macrophages were reprogrammed into M1 macrophages through macrophage polarization." (PMID 36145656, 2022). "In vivo, TLR7/8 agonists significantly suppressed tumor growth in CT26 tumor-bearing mice by remodeling the tumor microenvironment." (PMID 36476317, 2022). "Clinical translation of TLR7/8 agonists for cancer immunotherapyis an active area of research, with atleast 10 ongoing clinical trials evaluating their efficacy in a varietyof tumor types, many of which show promising early results (clinicaltrials.gov)." (PMID 36313164, 2022). "Many clinical trials attempt to enhance the anti-tumor effect by using agonists to cover both TLR7 and TLR8 targets." (PMID 36476317, 2022). "Among patients undergoing upfront surgery, stage, perivascular invasion, tumor differentiation grade 3, a high expression of TLR7, and a high expression of cytoplasmic TLR9 emerged as prognostic markers in univariate analysis." (PMID 35536778, 2022). "The tumor inhibition rate of the aPD-1-combined Smac-TLR7/8 hydrogel in the radiation-treated group was 11% higher than in the non-combined therapy group." (PMID 36145656, 2022). "Accordingly, anti-PD1 and IL-2 potentiated anti-tumor responses in TransCon TLR7/8 Agonist treated tumors." (PMID 36123697, 2022). "SC1, another TLR7 agonist, induces a potent TLR7-mediated anti-tumor immune response with a lower toxicity compared to R848." (PMID 36672572, 2022). "TLR5 and TLR7 have significant anti-tumor effects through dendritic cell-mediated cytotoxic T cells activation and regulatory T cell (Treg) inhibition." (PMID 35680568, 2022). "Clinical trials in metastatic cancers with imiquimod, a synthetic imidazoquinoline which activates TLR7, showed histological tumor regression and an increase in lymphoid immune infiltration." (PMID 35163420, 2022).